CTLA4 (cytotoxic T-lymphocyte associated protein 4)
Diseases named in the same sentence as CTLA4 in open-access papers (continued):
Sharing a sentence is not in itself a finding about the gene and the disease.
tumor (continued). "The immune checkpoint inhibitor immunotherapy of tumor mainly refers to a new treatment method of using PD-1 and CTLA4 inhibitors to enhance the immune function of the body by increasing the antitumor activity of T cells and achieve the purpose of eliminating the tumor." (PMID 34790582, 2021). "Next, to investigate whether the different response between CT-26 and Colon 26 was specific for anti-PD-1 or common for ICB, we tested anti-PD-1 and anti-CTLA-4 mAb in both CT-26 and Colon 26 tumor-bearing mice." (PMID 34774008, 2021). "In addition, the anti-CTLA-4 mAbs selectively reduce Tregs in the tumor sites by activating the Fc receptors, increasing the anti-tumor activity in cancer immunotherapy." (PMID 34806028, 2021). "In melanoma, increased histone methyltransferase Ezh2 expression during a-CTLA-4 immunotherapy, decreased the antigen presentation ability of cancer cells while its inactivation reversed the resistance to therapy and synergistically suppressed tumor growth." (PMID 33406696, 2021). "The immune checkpoints (i.e., PD1, CTLA4, and LAG3) were upregulated in the high-risk group, which might induce the depletion of CTLs, the tumor immune escape, and poor survival outcome." (PMID 33791227, 2021). "Increased expression of PD-L1 and CTLA-4 on tumor cells, following inhibition of the CSF-1R signaling, may partially account for the observed synergy." (PMID 33503832, 2021). "In addition to activated and memory T cells, several other immune cells also express CTLA-4 such as regulatory T cells (Tregs; which constitutively express CTLA-4) and tumor-infiltrating NK cells, and is induced on mouse NK cells upon IL-2 stimulation." (PMID 34531847, 2021). "Moreover, the expression of IFNγ and CD127, two canonical NF-κB-dependent genes, are required for tumor clearance upon CTLA-4/PD-1 dual blockade." (PMID 33572260, 2021). "CTLA-4/CD80, CD86 axis, which can be established between immune cells and tumoral cells, has been implicated in attenuating the development of anti-tumoral immune responses in the tumor microenvironment." (PMID 34067631, 2021). "Treating a mouse tumor model with PD-L1 and CTLA-4 inhibitors could promote the elimination of CSCs." (PMID 34912710, 2021). "In addition to activated CD4+ and CD8+ T cells, CTLA-4 is constitutively expressed on immunosuppressive FoxP3+ Tregs and plays a crucial role in Treg-driven suppression of anti-tumour immunity." (PMID 34299373, 2021). "Interestingly, CTLA4 is not only expressed by tumor infiltrating immune cells (TIICs) in EC, but is also expressed on cancer cells, which is an important part of tumor cell immune escape." (PMID 34513829, 2021). "Because cells were obtained from tumor biopsies prior to the administration of anti-CTLA-4 treatment, this finding suggests that cytotoxic NK cell infiltration could be predictive of anti-CTLA-4 response." (PMID 34376232, 2021). "Furthermore, ipilimumab reduces immunosuppression in the tumor microenvironment by blocking CTLA-4 on T regulatory cells." (PMID 34046035, 2021). "The CTLA-4 expression of intratumoural Tregs and the population of immuosuppresive tumour-associated M2 macrophage in the IPLD-treated mice did not change after 7 days of the last treatment, indicating the important role of CTLs in tumour inhibition." (PMID 33893275, 2021). "In addition to CTLA-4 and PD-1, additional checkpoint molecules involved in tumor immunosurveillance target ILCs." (PMID 33810032, 2021). "Combination treatment with PD-1/PD-L1 and CTLA-4 blockades might provide greater anti-tumor activity than single drugs as targeting both pathways may have synergistic effects." (PMID 33927616, 2021). "And there is discrepancy whether CTLA-4 expression in tumor cells has a good or a bad prognostic impact." (PMID 33906311, 2021).
tumor (continued). "In addition, bifunctional fusion proteins targeting PD-L1 or CTLA-4 and the TGFβR2 to inhibit TGF-β pathway and immune checkpoint simultaneously, were shown to be superior to PD-1 or CTLA-4 inhibitors in controlling tumor growth in vitro and in vivo." (PMID 34712672, 2021). "CD27 signalling has been found to be necessary to generate robust cytotoxic T cells, so CD27 agonists might further improve anti-PD-1 or CTLA-4 immunotherapy in cases where tumour-specific T cells are suboptimal." (PMID 33262520, 2021). "Here, a novel combination of photothermal therapy facilitated by a tumor targeted singe-walled carbon nanotube (SWCNT) bioconjugate and anti-cytotoxic T-lymphocyte-associated protein 4 (anti-CTLA-4) checkpoint inhibition is studied for treating metastatic breast cancer in an orthotopic murine model." (PMID 33411055, 2021). "CD4+ naive T cells (cluster 0 and cluster 2) at the core of the tumor express more immune checkpoint molecules, such as CTLA4, which has been used in clinical practice, and LAG3, HAVCR2, and TNFRSF9/CD137, which are currently undergoing clinical trials than those at other locations." (PMID 34513820, 2021). "Besides, CTLA-4 contributes to the development of the immunosuppressive tumor microenvironment in HCC via promoting Treg, IDO, and IL-10 production in the DCs." (PMID 34947886, 2021). "Intra-tumoral administration of anti-CTLA4 and/or anti-PD-1 has been shown to ensure optimal access to tumor-draining lymph nodes and in mouse models it has been shown to be equally efficacious as systemic delivery without unwanted immune-related side effects accompanying systemic treatment." (PMID 33864144, 2021). "Furthermore, Treg hamper anti-tumor immunity via the interaction of CTLA-4 with the co-stimulatory receptors CD80 and CD86, which are expressed by APC-like DC, resulting in the inhibition of their T cell stimulatory capacity." (PMID 33430105, 2021). "We found different tumor purities, immune scores, stromal scores, fractions of different immune cells, expression of several HLA genes and expression of five immune checkpoint molecules (CTLA4, CD274, HAVCR2, LAG3 and TIGHT) among UCEC subtypes." (PMID 34368124, 2021). "Antibodies against immune checkpoint molecules such as programmed cell death protein 1 (PD-1) and its ligand PD-L1, and the cytotoxic lymphocyte antigen-4 (CTLA-4), temporarily blocks inhibitory signals of T cells, thereby strengthening activation of anti-tumor T cell responses 1,2." (PMID 33391977, 2021). "Similarly, the optimal tumor inhibition was observed after the synergy with CBI by anti-CTLA-4 antibody (αCTLA-4)." (PMID 33420008, 2021). "Given that CTLA-4 and PD-1/PD-L1 pathways create a mechanism through which cancer cells avoid anti-tumour responses, the blockade of these pathways aimed at reversing T-cell exhaustion, and reinvigorating the anti-cancer response has been central to the development of novel therapies." (PMID 34944851, 2021). "Moreover, immune checkpoint blockade with either cytotoxic T lymphocyte–associated protein 4 (CTLA4) or PD1 antibody has been shown to elicit tumour vessel perfusion, conferring a significant increase in CD8+ T cell infiltration into tumours." (PMID 33917287, 2021). "This study indicated that changes in proteasome function caused by an increase in the levels of polyubiquitinated proteins in T-cells may indirectly affect CTLA-4 expression, thus mediating tumor evasion from immune surveillance." (PMID 34943817, 2021). "Therefore, CTLA-4 inhibitors induce anti-tumor immunity by blocking FOXP3+ Treg cells, resulting in enhanced inhibition of tumor cells." (PMID 34277408, 2021). "Therefore, CTLA-4 acts as a central element of immunologic tolerance to lessen the immune response in the tumor microenvironment." (PMID 34526987, 2021). "However, recent findings have demonstrated that CTLA-4 can also be expressed on tumoral cells and shield tumor cells from immune responses." (PMID 34067631, 2021).
tumor (continued). "In addition, macrophages synergize with anti-CTLA-4 immunotherapy as well as actively participate in tumor cell clearance with tumor-specific mAb." (PMID 34572013, 2021). "High risk scores correlated significantly negatively with high CTLA-4 and HAVCR2 expression and higher median inhibitory concentration of common anti-tumor chemotherapeutics (e.g., cisplatin, paclitaxel, gemcitabine) and targeted therapy (e.g., erlotinib and gefitinib)." (PMID 34438369, 2021). "In a mouse glioma model, combination of oHSV with PD-1 and CTLA-4 blockade led to tumor regression in most mice and prevented tumor engraftment on tumor re-challenge in mice with initial tumor regression, suggesting that this combination therapy generated a lasting anti-tumor immune response." (PMID 34277419, 2021). "Furthermore, the combination of T-DM1 with CTLA-4/PD-1 blocking antibodies enhances T cell infiltration and promotes tumor rejection and immunological memory formation." (PMID 34944971, 2021). "Interestingly, in sunitinib-treated mice, there is a higher infiltration of CD4+ and CD8+ within the tumor with a lower CTLA-4 and PD-1 expression, preventing T cells exhaustion." (PMID 34064508, 2021). "In addition, CTLA‐4 is a key target for cancer immunotherapy, whereby antibodies to CTLA‐4 revolutionized cancer treatment by triggering (auto)immune responses to tumours." (PMID 33960403, 2021). "Especially, CTLA-4, PD-1, and PD-L1 antibodies have curative effect on tumor treatment." (PMID 34970268, 2021). "To account for the genetic-drivers that may underlie responses to ICI and to be able to use C57BL6 syngeneic tumor model, we used B6/lpr mice and a continuous administration of anti-PD-1 and anti-CTLA-4 antibodies." (PMID 33571254, 2021). "Moreover, combined CD44-targeted NIR-PIT with programmed cell death protein 1 (PD-1) or CTLA4 checkpoint blockade was more effective in combination than as single therapies in syngeneic mouse models, including a minimally immunogenic tumor." (PMID 34064074, 2021). "Importantly, combined blockade of IL-6 and CTLA-4 improves survival of tumor-bearing mice by reducing infiltration of PD1+CD8+ T cells and M2 macrophages in TME." (PMID 34093869, 2021). "In addition to the use of anti-PD-1/PD-L1 or anti-CTLA-4 antibodies, the search of immune inhibitory blockade mechanisms has led to the study of metabolic pathways used by malignant cells to shape tumor microenvironment and to induce immune modulation." (PMID 34557553, 2021). "In a mouse model of checkpoint blockade immunotherapy, d42m1 clone T3 tumor cells could grow in wild-type mice, but were rejected following anti-PD-1 or anti-CTLA-4 immunotherapy." (PMID 34885172, 2021). "Similarly, combination of RT (3 × 8 Gy) with anti-CTLA-4 therapy induced tumor growth control in a MC38 xenograft model." (PMID 33803620, 2021). "Recently, immunotherapy that includes programmed cell death-1 (PD-1), programmed cell death ligand 1 (PD-L1), and cytotoxic T-lymphocyte antigen 4 (CTLA-4) inhibitors, which enhance anti-tumor activity, has revolutionized the therapeutic strategy for multiple malignancies." (PMID 34122422, 2021). "On the other side, blocking CTLA-4 can contribute to increase TIL on the BC tumor microenviroment." (PMID 34829916, 2021). "In tumor eradication, anti-CTLA-4 antibodies could possibly induce the selective depletion of Tregs cells via Fc receptor-dependent cytotoxicity of macrophages or NK cells." (PMID 34572844, 2021). "Blocking acidification prior to anti-PD-1 or anti-CTLA-4 may lead to efficient anti-tumor responses." (PMID 33807867, 2021). "Indeed, there are currently one CTLA-4 and six PD-1/PD-L1 inhibitors approved across ten tumor types and numerous stages of cancer." (PMID 33807608, 2021). "Also, the combination of triple therapy using checkpoint inhibitors (anti-CTLA-4 and anti-PD-1), and immune-virotherapy showed effective M1 polarization of macrophages and tumor eradication." (PMID 34168976, 2021).
tumor (continued). "Clinical evidence has shown that anti–CTLA-4 therapy can enhance the activation of effector T cells, increase the ratio of effector T cells to Treg, and promote the transport of activated T cells to tumor tissues." (PMID 34744733, 2021). "However, TIM-3 expression, along with the expression of other T cell exhaustion markers such as PD-1 and CTLA-4, is lower in the non-tumor microenvironment (NTME) and the peripheral blood than the TME." (PMID 34940257, 2021). "Furthermore, in parallel to the increased expression of PD-1 and PD-L1, a high expression of CTLA-4 was observed on tumor cells treated with PD-1/PD-L1 antagonists, whereas a decreased expression was detected in case of PD-1/PD-L1 agonistic treatments." (PMID 34201082, 2021). "Additionally, the combination of PL1-OX40 mRNA and anti-OX40 antibody significantly boosts the antitumor immune response to anti-PD-1 + anti-CTLA-4 antibodies in the B16F10 tumor model." (PMID 34907171, 2021). "In a PC mouse model, the simultaneous administration of IL-15, anti-CTLA-4, and anti-PDL-1 was associated with increased number of CD8+ T cells, T cell lytic activity, and IFN-γ release, decreased tumor growth, and improved mice survival (compared to IL-15 alone)." (PMID 34830179, 2021). "Studies have shown that tumor cells of TNBC patients express CTLA-4 in different cell compartments." (PMID 35111680, 2021). "Finally, we investigated the association between the constructed risk model and tumor mutational burden (TMB), abundance of tumor-infiltrating immune cells (TICs) as well as immunotherapeutic targets (PDL-1, PD-1, and CTLA4) in THCA." (PMID 34976004, 2021). "To this aim, we produced the anti-PD-1 mAb with IgG4 isotype, and anti-CTLA-4 mAb with IgG1 isotype, in order to better compare them to Nivolumab and Ipilimumab, IgG4 and IgG1, respectively, to evaluate their isotype-independent effects on tumor cells." (PMID 34201082, 2021). "Because of the significant association between TMCs and tumor microenvironment, TMB, and PD-1/PD-L1/CTLA4, we hypothesis that TMCs may have predictive value in immunotherapeutic response." (PMID 34899684, 2021). "Here, we investigated the expression of CTLA-4 in the membrane of T cells and tumor cells." (PMID 34526987, 2021). "Additionally, CTLA-4 and PD-1 utilize distinct mechanisms of the Akt pathway, which can function for synergistic tumor regulation and IRAEs." (PMID 33614750, 2021). "This phenomenon implicates a large number of biological processes, and one of them is immune checkpoint induction, such as cytotoxic T-lymphocyte-associated protein 4 (CTLA-4) or PD-1, which have suppressive functions against activation of anti-tumor lymphocytes." (PMID 34885109, 2021). "For example, upregulation of IL-12r or CTLA-4 in both the HTB-1 and SiHa models may suggest a combination with an IL-12 or CTLA-4 modulating agent which may enhance the observed anti-tumor response." (PMID 32373533, 2020). "However, research in the field of neural tumor immunotherapy currently mainly focuses on CTLA-4 and PD-1/PD-L1 blockade." (PMID 32695752, 2020). "Since these data may support testing new generation of anti-CTLA-4 antibodies in clinical trials, we decided to perform an in-depth analysis of tumor-infiltrating T cells in human to predict selectivity of anti-CTLA-4 antibody-induced Treg depletion." (PMID 31991588, 2020). "The expression of CTLA-4 on different types of tumor cells has been also demonstrated." (PMID 33519815, 2020). "Pre-treatment with IFN-γ, the TLR3 ligand poly (I:C), and anti-IL-10 Ab, which attract IFN-γ-producing NK cell infiltration into tumor sites, rendered tumors sensitive to checkpoint blockade therapy (e.g., mAbs recognizing CTLA-4 and PD-1), leading to increased cure rates." (PMID 32714324, 2020). "CD80 expression on tumor stem cells directly decreases T-cell activity upon engaging with CTLA-4." (PMID 32380703, 2020).
tumor (continued). "Similarly, the combination of T-DM1 and anti PD1/CTLA4 agents fostered both innate and adaptive immune response, ultimately resulting in tumor rejection in a HER2-expressing orthotopic tumor model." (PMID 36046385, 2020). "Flank tumor growth analysis demonstrated an average mouse receiving ISV had an additional 20% decrease (95% CI 18% to 21% reduction, p<0.001) in geometric mean of tumor volume for each additional day of treatment, as compared with an average mouse receiving α-CTLA-4 alone." (PMID 32690669, 2020). "Interestingly, CTLA-4-positive SK-BR-3 and LNCaP cancer cells showed higher levels of EGFR than those detected on cells expressing low levels of CTLA-4, such as tumor MCF-7 cells or H9c2 cardiomyoblasts." (PMID 32024070, 2020). "Importantly, the proportion of CD8+ T cells recovered from tumor fragments after CTLA-4 blockade was sustained when TIL cultures were rapidly expanded." (PMID 32127601, 2020). "However, ICIs-related toxicities were accompanied with the enhanced anti-tumor responses following the CTLA-4 blockade." (PMID 33123120, 2020). "However, when anti-CTLA-4 was combined with either the 5, 10, or 25 mg/kg OXi4503 doses, no further significant improvement was found, despite 30% of mice treated with OXi4503 (25 mg/kg) and anti-CTLA-4 resulting in complete tumor control." (PMID 32640548, 2020). "Conversely to CTLA-4 and PD-1, TIGIT was associated to NK-cell exhaustion in a mouse model of colon cancer and TIGIT blockade was capable of reverting the condition allowing NK cells to trigger an anti-tumor immune response." (PMID 33255582, 2020). "Indeed, the binding of CTLA-4 by ipilimumab on Treg within the tumor tissue would likely promote Treg depletion by antibody-dependent cellular cytotoxicity (ADCC) and phagocytosis by NK cells and macrophages." (PMID 32265933, 2020). "Interestingly, in this combination setting, there was an increase in Fcγ receptor IV expression on macrophages, resulting in greater antibody-dependent macrophage-mediated depletion of CTLA-4-positive Tregs in the tumour." (PMID 33352882, 2020). "Additionally, the same group showed that pairing ablation with an anti-CTLA-4 antibody resulted in protection against tumor re-challenge." (PMID 32672126, 2020). "Moreover, hypoxia counteracts the desired effects of CHI, such as PDCD1 or CTLA4 inhibitors leading to CHI resistance of tumor cells." (PMID 33240813, 2020). "CTLA-4 plays a pivotal role in inducing peripheral tolerance and maintaining immunologic homeostasis but it is believed to be a negative regulator within the anti-tumor immunity." (PMID 33123120, 2020). "In mouse models bearing progressive sarcomas, anti‐PD‐1 and anti‐CTLA‐4 agents could reactivate neoantigen‐specific T cells in tumors and induce tumor rejection." (PMID 32997401, 2020). "Combination might intensify proliferation and effector functions of tumor-specific T cells induced by DC vaccination by blocking inhibitory immune checkpoints with anti-CTLA-4 or anti-PD-1 mAbs." (PMID 31980913, 2020). "Patient distribution according to locations and densities of tumor-infiltrating CTLA-4+ cells." (PMID 32785290, 2020). "In tumors, CTLA-4 is overexpressed to suppress the activation of immune cells which could have been successful in reaching the tumor site (generally referred to as tumor infiltrating lymphocytes—TILs)." (PMID 33092131, 2020). "However, in some syngeneic mouse models, Tregs suppress this host anti-tumor immunity mediated by inhibiting DC function through the CTLA4 axis." (PMID 32937841, 2020). "In addition to PD-1 and CTLA-4, numerous other immune checkpoints have been shown to stimulate anti-tumor immunity." (PMID 33033688, 2020). "It has been known that immunosuppressive Tregs express cytotoxic T-lymphocyte-associated protein 4 (CTLA-4) at higher levels and a combination of programmed cell death 1 (PD-1) and CTLA-4 blockades increases tumor-infiltrating effector T cell and reduces tumor-infiltrating Tregs." (PMID 33352665, 2020).